TMEM80 (transmembrane protein 80)
Synonyms: FLJ38216
Tractability: Antibody: UniProt predicts a signal peptide or a membrane-spanning region.
Gene: Protein-coding gene on chromosome 11 (695,591 to 705,028, forward strand). Ensembl gene ENSG00000177042.
Subcellular location: Membrane; Cell projection, cilium
Subcellular location (Human Protein Atlas): Golgi apparatus
Gene Ontology:
Molecular function: protein binding
Biological process: non-motile cilium assembly
Cellular component: ciliary transition zone; cilium; membrane
Genetic constraint (gnomAD): Loss-of-function variants: 17 observed, 14.8 expected, observed/expected ratio (o/e) 1.15, 90% interval 0.78 to 1.7. The upper end of that interval is the gene's LOEUF score, 1.7, which puts it in group 6 of 6, group 1 being the genes least tolerant of losing a copy. Missense variants: 167 observed, 187.56 expected, observed/expected ratio (o/e) 0.89, 90% interval 0.78 to 1.01. Synonymous variants: 92 observed, 92.46 expected, observed/expected ratio (o/e) 1, 90% interval 0.84 to 1.18.
Homologues: Orthologues: chimpanzee TMEM80 (97% identical), macaque TMEM80 (90% identical), pig TMEM80 (76% identical), rat Tmem80 (76% identical), dog TMEM80 (70% identical), mouse Tmem80 (63% identical), tropical clawed frog tmem80 (60% identical), Caenorhabditis elegans mks-2 (24% identical), Drosophila melanogaster CG11760 (23% identical), Drosophila melanogaster TMEM216 (22% identical). Paralogues in human: TMEM216 (40% identical), TMEM17 (24% identical).
Diseases named in the same sentence as TMEM80 in open-access papers:
TMEM80 is named in the same sentence as 1 disease in open-access papers, as found by Europe PMC text mining. Sharing a sentence is not in itself a finding about the gene and the disease. The quoted sentences say what the papers report.
ciliopathy (1 paper, 2016). A genetic disorder of the cellular cilia or the cilia anchoring structures, the basal bodies, or of ciliary function. "Aside from Tmem218 and Tmem80, one of the few TZ proteins that remains to be linked to one or more ciliopathies is Tmem17." (PMID 26982032, 2016). "It will be interesting to confirm and further investigate in mammalian cells our overall model for TZ assembly as well as obtain evidence for the involvement of the novel TZ proteins we uncovered (Tmem218 and Tmem80) in ciliopathies." (PMID 26982032, 2016).